GPR85 (G protein-coupled receptor 85)
Description:
Orphan receptor.
Synonyms: SREB2; SREB
Tractability: Small molecule: it belongs to a druggable protein family. Antibody: its Gene Ontology location is reachable by antibodies, with high confidence; UniProt places it where antibodies can reach, with medium confidence; UniProt predicts a signal peptide or a membrane-spanning region.
Target class: Family A G protein-coupled receptor; Membrane receptor
Gene: Protein-coding gene on chromosome 7 (113,078,331 to 113,087,778, reverse strand). Ensembl gene ENSG00000164604.
Subcellular location: Cell membrane; Endoplasmic reticulum
Gene Ontology:
Molecular function: protein binding; G protein-coupled receptor activity
Biological process: signal transduction; G protein-coupled receptor signaling pathway
Cellular component: endoplasmic reticulum; plasma membrane; membrane
Genetic constraint (gnomAD): Loss-of-function variants: 7 observed, 22.13 expected, observed/expected ratio (o/e) 0.32, 90% interval 0.18 to 0.59. The upper end of that interval is the gene's LOEUF score, 0.59, which puts it in group 2 of 6, group 1 being the genes least tolerant of losing a copy. Missense variants: 299 observed, 467.9 expected, observed/expected ratio (o/e) 0.64, 90% interval 0.58 to 0.7. Synonymous variants: 167 observed, 173.72 expected, observed/expected ratio (o/e) 0.96, 90% interval 0.85 to 1.09.
Homologues: Orthologues: dog GPR85 (100% identical), guinea pig GPR85 (100% identical), mouse Gpr85 (100% identical), rabbit GPR85 (100% identical), rat Gpr85 (100% identical), macaque GPR85 (99% identical), tropical clawed frog gpr85 (99% identical), pig GPR85 (96% identical), zebrafish gpr85 (94% identical). Paralogues in human: GPR173 (62% identical), GPR27 (52% identical).
Diseases named in the same sentence as GPR85 in open-access papers:
GPR85 is named in the same sentence as 22 diseases in open-access papers, as found by Europe PMC text mining. Sharing a sentence is not in itself a finding about the gene and the disease. The quoted sentences say what the papers report.
schizophrenia (7 papers, 2012 to 2024). A major psychotic disorder characterized by abnormalities in the perception or expression of reality. "GPR85 previously named as, Super conserved receptor expressed in brain-2, SREB2, has been associated with the brain, and has been linked to autism spectrum disorder and schizophrenia, so far." (PMID 38895631, 2024). "In a family-based association test (FBAT) with human samples, two alleles of the GPR-85 gene were identified to be associated with schizophrenia, the presence of which is associated with a decrease in hippocampal cortex." (PMID 38256919, 2024). "GPR85 is involved in predisposing patients to a high risk of schizophrenia; two GPR85 SNPs in moderate linkage disequilibrium have been associated with schizophrenia, but mutations in GPR85 have not been found in patients with schizophrenia." (PMID 25780553, 2015). "In the present study, we focused on GPR85 as a candidate gene for ASD because the C-terminal amino acid sequence of GPR85 [Thr-Cys-Val-Ile (YCVI)] is classified as a type II PDZ-binding motif, and GPR85 is a risk factor for schizophrenia." (PMID 25780553, 2015). "GPR85 is abundantly expressed in brain structures that exhibit high levels of plasticity, and GPR85 is involved in determining the size of the brain, regulating diverse behaviors, and may cause schizophrenia." (PMID 36743290, 2022). "GPR85 is a risk factor for schizophrenia, suggesting that GPR85 could be related to the molecular pathogenesis of not only ASD but also schizophrenia via interaction with PSD-95 or SAP102." (PMID 25780553, 2015). "Another study showed the direct influence of GPR-85 expression on brain size, behavior, and vulnerability to schizophrenia by comparing characteristics between transgenic mice and wild-type mice with knock-outs." (PMID 38256919, 2024). "During the study on the common molecular basis in the psychiatric disorders including schizophrenia and ASD, we found that the C-terminal sequence of GPR85 was linked with NLGN and PDZ proteins including PSD-95 in the brain." (PMID 25780553, 2015). "To examine the common molecular basis of schizophrenia and ASD, we searched for GPR85 mutations in Caucasian and Japanese ASD patients." (PMID 25780553, 2015). "The GPR-85 expression distribution showed an intense expression in the thalamus and the dentate gyrus of the hippocampus, with both regions being involved in the pathophysiology of schizophrenia." (PMID 38256919, 2024). "From the currently available studies regarding the potential association between GPR expression and schizophrenia, we identified twelve studies out of which two were on GPR-52 expression, four on GPR-85 expression, four on GPR-88 expression, and one on GPR-139 expression." (PMID 38256919, 2024). "Thus, mutated GPR85 could be associated with the molecular pathogenesis of ASD, and GPR85 may be a common molecular target for ASD and schizophrenia." (PMID 25780553, 2015). "G protein-coupled receptor 85 (GPR85) was found to be the most upregulated gene, though this receptor is mainly expressedin the brain and contributes to various neurological diseases such as schizophrenia; thereis limited research correlating this receptor to hematological cancers." (PMID 39698279, 2024).
breast carcinoma (4 papers, 2019 to 2023). "In addition, the activation of cancer-associated fibroblasts through the CXCL14/GPR85 pathway has been shown to leads to EMT and progression in breast cancer." (PMID 37056937, 2023). "Activation of GPR85 by CXCL14 triggered ERK1/2 and AKT pathway activation, which promoted breast cancer cell progression." (PMID 32708730, 2020). "Recent studies have suggested that the G protein-coupled receptor GPR85 and atypical chemokine receptor 2 (ACKR2) could be the target of CXCL14 in breast cancer cells." (PMID 32708730, 2020).
autism (1 paper, 2015). Persistent deficits in social interaction and communication and interaction as well as a markedly restricted repertoire of activity and interest as well as repetitive patterns of behavior. "Two independent GPR85 mutations, T1033C (M152T) and G1239T (V221L), were found in male autism patients from Japanese families." (PMID 25780553, 2015).
epilepsy (1 paper, 2015). A brain disorder characterized by episodes of abnormally increased neuronal discharge resulting in transient episodes of sensory or motor neurological dysfunction, or psychic dysfunction. "Individuals with either the M152T or V221L mutation in GPR85 presented with similar clinical phenotypes; they exhibited ASD with mild intellectual disability, the ability to speak some simple words, and no epilepsy." (PMID 25780553, 2015).
glioblastoma (1 paper, 2019). The most malignant astrocytic tumor (WHO grade IV). "Moreover, as for GPR85, our SAGE data in glioblastoma samples and an RNA-seq analysis on GBM stem-like cells we recently performed, showed only a barely detectable level of ACKR2 mRNA expression in tumor samples and data not shown." (PMID 31117166, 2019).
lung carcinoma (1 paper, 2023). "Therefore, we investigated the role of ACKR2, CXCR4, and GPR85 in lung cancer." (PMID 37056937, 2023). "A meta‐analysis in all lung cancer tissues containing adenocarcinoma (LUAD) found that the expression of ACKR2 but not the other candidate receptors, CXCR4 and GPR85, was up-regulated in lung cancer studies." (PMID 37056937, 2023). "Next, lung cancer cells transfected with the ACKR2 siRNA or incubated with ACKR2 neutralized antibody markedly abolished CXCL14‐induced cell migration and cell movement, but not CXCR4, and GPR85." (PMID 37056937, 2023).
Obesity (1 paper, 2025). Accumulation of substantial excess body fat. "GPR85 expression is influenced by obesity, suggesting a link to metabolic state." (PMID 41514760, 2025).
tumor (3 papers, 2019 to 2023). "GPR85, a candidate receptor for CXCL14, was found on the cell membranes of primary mammary fibroblasts obtained from benign breast mass (normal-associated fibroblasts, NAFs)." (PMID 31014014, 2019). "Thus, GPR85 may be a good target molecule for further clarification of context-dependent CXCL14 functions on tumor progression." (PMID 31014014, 2019).
infection (2 papers, 2014 to 2022). The state of being infected such as from the introduction of a foreign agent such as serum, vaccine, antigenic substance or organism. "Within the locus we also identified host genes whose expression increased (Samd9l, Asns, Gpr85, and Tfpi2) or decreased (Pon1, Hepacam2, Tmem106b, and Pppr9a1) 2-fold (P < 0.05) 72 hours after infection with H5N1 IAV in D2, B6 or both mouse strains." (PMID 25418976, 2014).
brain disorder (1 paper, 2018). A disease affecting the brain or part of the brain. "Considering the associations of GPR85/SREB2 with ASDs and SCZ, more investigations about the functional relationship between Shank3 and GPR85 would provide information on the detailed mechanisms of activity-dependent synaptic regulation and their potential implications in multiple brain disorders." (PMID 30233305, 2018).
hematological cancers (1 paper, 2024). "Among these GPCRs, GPR85, GPR65, and GPR183 have varying numbers ofstudies in the field of hematological cancers and pediatric ALL." (PMID 39698279, 2024).
GPR85 also shares sentences with these, for which no sentence is quoted: autism spectrum disorder (2 papers); adenocarcinoma (1); anaplastic glioma (1); cancer (1); cavernous hemangioma (1); glioma (1); Intellectual disability (1); leukemia (1); melanoma (1); neurological diseases (1); psychiatric disorder (1).